MIR409 (microRNA 409)
Synonyms: hsa-mir-409; MIRN409; mir-409
Gene: MicroRNA gene on chromosome 14 (101,065,300 to 101,065,378, forward strand). Ensembl gene ENSG00000199107.
Gene Ontology:
Biological process: miRNA-mediated post-transcriptional gene silencing
Cellular component: RISC complex
Homologues: Orthologues: chimpanzee ptr-mir-409 (100% identical), mouse Mir409 (97% identical), guinea pig MIR409 (92% identical), mouse Gm54371 (61% identical). Paralogues in human: MIR323B (70% identical), MIR323A (63% identical), MIR154 (59% identical), MIR410 (58% identical), MIR1185-1 (57% identical), MIR487B (57% identical), MIR494 (57% identical), MIR1185-2 (54% identical), MIR487A (54% identical), MIR656 (53% identical), MIR382 (52% identical), MIR496 (52% identical), and 4 more.
Diseases named in the same sentence as MIR409 in open-access papers:
MIR409 is named in the same sentence as 2 diseases in open-access papers, as found by Europe PMC text mining. Sharing a sentence is not in itself a finding about the gene and the disease. The quoted sentences say what the papers report.
cancer (1 paper, 2024). A tumor composed of atypical neoplastic, often pleomorphic cells that invade other tissues. "ABCC9 has been linked to drug resistance in cancer, while MIR311 and MIR409 are thought to regulate gene expression via hypomethylation, thereby promoting cancer progression." (PMID 39649173, 2024).
MIR409 also shares sentences with these, for which no sentence is quoted: squamous cell carcinoma (1 paper).